FAM110D (family with sequence similarity 110 member D)
Synonyms: GRRP1; FLJ14050
Tractability: No criterion of Open Targets' tractability assessment is met for any kind of drug.
Gene: Protein-coding gene on chromosome 1 (26,159,047 to 26,163,962, forward strand). Ensembl gene ENSG00000197245.
Gene Ontology:
Molecular function: protein binding
Genetic constraint (gnomAD): Loss-of-function variants: 1 observed, 0.21 expected, observed/expected ratio (o/e) 4.75. That is too few expected variants to judge how well the gene tolerates losing a copy. Missense variants: 325 observed, 239.48 expected, observed/expected ratio (o/e) 1.36, 90% interval 1.24 to 1.49. Synonymous variants: 155 observed, 115.08 expected, observed/expected ratio (o/e) 1.35, 90% interval 1.18 to 1.54.
Homologues: Orthologues: chimpanzee FAM110D (99% identical), macaque FAM110D (98% identical), dog FAM110D (92% identical), pig FAM110D (89% identical), guinea pig FAM110D (89% identical), rat Fam110d (87% identical), mouse Fam110d (86% identical), rabbit FAM110D (72% identical), zebrafish fam110d (41% identical), tropical clawed frog fam110d (30% identical). Paralogues in human: FAM110C (29% identical), FAM110A (26% identical), FAM110B (24% identical).
Diseases named in the same sentence as FAM110D in open-access papers:
FAM110D is named in the same sentence as 3 diseases in open-access papers, as found by Europe PMC text mining. Sharing a sentence is not in itself a finding about the gene and the disease. The quoted sentences say what the papers report.
atherosclerosis (1 paper, 2025). A disease characterized by the build-up of fatty material and calcium deposition in the arterial wall resulting in partial or complete occlusion of the arterial lumen. "Collectively, overexpression of FAM110D and PLVAP in HAECs specifically impacts GRN195 gene activity along with several atherosclerosis-relevant EC phenotypes including chromatin condensation, adhesion, mitochondrial activity and proliferation." (PMID 40211055, 2025).
lung adenocarcinoma (1 paper, 2024). A carcinoma that arises from the lung and is characterized by the presence of malignant glandular epithelial cells. "There are few studies on FAM110D gene, but some studies have found that another FAM110 gene, FAD110B, can inhibit the growth and invasion of lung adenocarcinoma by inactivating the Wnt/β-catenin signaling pathway." (PMID 38568089, 2024).
tumor (1 paper, 2021). "Interestingly, high expression FAM110D and CASQ2A suggested better prognosis, whereas they were upregulated in tumor samples." (PMID 34409040, 2021). "Interestingly, FAM110D and CASQ2 were overexpressed in tumor samples, whereas a higher level of them represented longer OS time, indicating such underlying mechanism as stemness characteristic might lie in their prognostic value." (PMID 34409040, 2021).